CTSB (cathepsin B)
Diseases named in the same sentence as CTSB in open-access papers (continued):
Sharing a sentence is not in itself a finding about the gene and the disease.
cancer (continued). "The prognostic value of CTSB and CTSL was further explored in pan-cancers." (PMID 35155389, 2022). "Thus, the localized accumulation of CTSB-PPP in tissues with high protease activity, along with the fluorescence of pheophorbide-a, can be used in cancer bioimaging techniques." (PMID 35631388, 2022). "Also there is a lack of experimental data and mechanism research in understanding the link between the cancer data on SARS-CoV-2 and the potential role for CTSB/L; further experimental data is therefore needed." (PMID 35155389, 2022). "Cathepsin B and Cathepsin D release into the cytosol promoted the cleavage and activation of BID, and Dcf1 also decreased the expression of Bcl‐2 to induce the release of proapoptotic factors and enhance the levels of cancer suppressors." (PMID 34799992, 2022). "Thus, the PD-NPs can lead safe and more effective cancer immunotherapy by inducing ICD preferentially in targeted cancer cells and minimizing the off-target toxicity via cathepsin B-specific drug release." (PMID 35265195, 2022). "Nanoneedle sensors can identify CTSB positive (+ve) cancer cells and CTSB negative (−ve) cancer cells in mixed cultures." (PMID 36133409, 2022). "Conversely, STUMPs and LMSs shared 47 CNAs, in particular gain/amplification of the regions containing cancer related genes as PRKDC (8q11.21; eight samples), MLL3 (7q36.1; seven samples), ROCK2 (2p25.1; six samples), CTSB (8p23.1; six samples) and STAT2 (12q13.2; five samples)." (PMID 33557274, 2021). "Next, enzymes, overexpressed by cancer cells or neovascular tissue in tumors, capable of selective cleavage of prodrugs carrying a peptide substrate moiety, offer several examples: e.g., MMP, cathepsin B, β-glucuronidase, and PSA and PSMA." (PMID 33673582, 2021). "Enhanced expression of CD147 at the invasive front of HCC cell groups promoted HCC cells collective invasion via upregulating cathepsin B expression and targeting CD147 would be valuable for the development of novel therapeutic modalities against invasion and metastasis of cancer." (PMID 32727598, 2020). "Since cathepsin B plays a critical role in the proliferation and metastasis of tumors, it is expected that UNA may facilitate chemotherapy of cancer by targeting cathepsin B of cancer cells." (PMID 33147723, 2020). "RNAi-mediated downregulation of cathepsin B or the absence of cathepsin B induces apoptosis in cancer." (PMID 31752209, 2019). "The sensor discriminates CTSB positive (+ve) cancer cells from CTSB negative (−ve) cells in a mixed culture." (PMID 26197973, 2015). "In non-IBC, the cysteine protease cathepsin B (CTSB) is known to be involved in cancer progression and invasion; however, very little is known about its role in IBC." (PMID 21199580, 2011). "IHC scoring results revealed a statistical significance (P = 0.025) in the level of expression of CTSB in IBC versus non-IBC carcinoma cells." (PMID 21199580, 2011). "To further localize cellular expression of CTSB in IBC versus non-IBC carcinoma cells, we used IHC to stain CTSB in paraffin embedded tissue sections." (PMID 21199580, 2011). "Gene Ontology (GO) and Kyoto Encyclopedia of Genes and Genomes (KEGG) analyses revealed that the top upregulated genes (start vs. end) in cancer‐pre cells (Curve1 and Curve2) were enriched in antigen processing and presentation pathways, such as CD74, HLA‐DRB1, HLA‐DRA, PSME1/2, and CTSB." (PMID 40860436, 2025). "Moreover, targeting cathepsin B with cycloastragenol has been shown to enhance CD8+ T cell-mediated antitumor immunity by inhibiting MHC-I degradation, further supporting the pivotal role of MHC-I in modulating immune responses to cancer." (PMID 39601759, 2025).
cancer (continued). "However, none of these inhibitors have shown strong enough anticancer effects to be clinically available, and there are currently no FDA-approved cathepsin B inhibitors for cancer treatment." (PMID 38500921, 2024). "Cathepsin B is a lysosomal protease with predominant expression in mammalian lysosomes and it is commonly found to be overexpressed in various types of cancer cells, therefore, it enables the precise and effective release of the MMAE payload in the targeted cancer cells." (PMID 37727735, 2023). "Expression of these genes like cathepsin B are elevated in many but not all cancers." (PMID 37064116, 2023). "It has been shown that CTSB secreted by fibroblasts induces elevated expression of stearoyl-CoA desaturase 1 in B16F10 cells through annexin A2 and increased stearoyl-CoA desaturase 1 expression ultimately affects cancer cell proliferation and metastatic colonization." (PMID 37576397, 2023). "Although CTSB/L indicates an increased level of immune cell infiltration in various cancers, the prognosis might not be better because the immune cells tend to be blunt and dysfunctional." (PMID 35155389, 2022). "However, the expressions of CTSB/L in healthy individuals and cancer patients remain not fully elucidated yet." (PMID 35155389, 2022). "Moreover, it raises the importance of Cathepsin B and the interest to develop inhibitor peptides targeting its interaction with NLRP3, an early and common event, to inhibit IL-1β production in inflammatory diseases or cancer." (PMID 32328491, 2020). "The same study demonstrated that LF-derived cathepsin B (CTSB) induced SCD1 overexpression in B16F10 cells via annexin A2 (ANXA2) and the PI3K/Akt/mammalian/mechanistic target of rapamycin (mTOR) pathway, which is critical for cellular metabolism and cancer progression." (PMID 31284458, 2019). "Since RD‐N induced BRCA1 degradation through CTSB, we sought to determine whether down‐regulation of BRCA1, which is critical in maintaining genomic integrity by promoting homologous recombination (HR), would affect RD‐N mediated apoptosis of cancer cells." (PMID 30565390, 2019). "Furthermore, it has been shown that cathepsin B can reach peripherally located vesicles in cancer cells by a pathway that is independent of M6P and most probably driven by sorting signals located within the pro-peptide region of the enzyme." (PMID 21835049, 2011). "Furthermore, there was a difference between IBC and non-IBC carcinoma cells in regard to co-expression of cathepsin B and caveolin-1." (PMID 22093547, 2011). "While the disbalance between CtsB and StfA may represent a reliable disease progression marker, this phenomenon should be explored in the specific context of tissue and cancer type, and to our knowledge, no previous studies have investigated CtsB and StfA in RCC." (PMID 35563761, 2022). "This includes actin-binding protein gelsolin a protein involved in cell motility and required for cancer cell invasion, matrix metalloproteases MMP9 which degrade extracellular matrix and promotes invasion, metastasis-associated proteins S100A4/metastasin and cathepsin B (data not shown)." (PMID 19753117, 2009). "Because the inhibition of cathepsin expression or activity by a specific siRNA or inhibitor, respectively, did not completely block MDA-MB-231 cancer cell invasion, the role of MMP-9 in synergistic action with CTSB or CTSS was examined." (PMID 30185799, 2018).
infection (182 papers, 2005 to 2026). The state of being infected such as from the introduction of a foreign agent such as serum, vaccine, antigenic substance or organism. "We observed an increase in cellular cathepsin B activity in LRSAM1-deficient cells upon infection, which confirmed the higher activity of autophagy in these cells compared to NTC control cells." (PMID 40861495, 2025). "For example, CtsB-deficient cDCs produce less IFN-α/β after modified vaccinia virus Ankara (MVA) infection." (PMID 41369389, 2025). "This supports a model in which the intracellular cathepsin B loss is a distinct process from the global lysosomal protein secretion observed during infection." (PMID 40274809, 2025). "We recognized that the cells in culture exhibited a distribution of the expression levels of TMPRSS2 and Cathepsin B/L and thus had a distribution of susceptibilities to infection via the two pathways." (PMID 33290397, 2020). "While we did not observe differences in NPC1 mRNA expression between infected and uninfected monocytes, expression of known EBOV entry factors like cathepsin B and L were associated with infection." (PMID 33159858, 2020). "Impaired infection correlates with loss of the expression of cathepsin B, known to be essential for EBOV entry." (PMID 30655525, 2019). "In RAW264.7 cells MNV infection clearly causes apoptosis and programmed cell death, most likely through an atypical pathway involving survivin and possibly other players such as cathepsin B." (PMID 24599381, 2014). "Other groups have associated increased cathepsin B activity with infections by several other viruses, such as human Papilloma virus, Influenza A virus, Adeno-associated virus, and Norovirus." (PMID 22693552, 2012). "Statistical analysis reveals that susceptibility to the CD4-independent mNDK vector infection was reverse-correlated with cathepsin B activity of the target cells." (PMID 21541353, 2011). "Cathepsin B activity was inversely correlated with cellular susceptibility to the CD4-independent HIV-1 vector infection." (PMID 21541353, 2011). "In light of our findings that cathepsin B loss is dependent on a functional Dot/Icm T4SS, we aimed to determine which C. burnetii effector protein(s) might be responsible for loss of cathepsin B during infection." (PMID 40274809, 2025). "As our analysis revealed a higher fluorescence intensity in infected cells and considering that cathepsin B activity is directly linked to acidic lysosomal pH, our data strongly suggest elevated cathepsin B activity throughout the infection, implying concurrent lysosomal acidification." (PMID 38980070, 2024). "Cathepsin B has been reported for its role in proteins degradation related to the lysosomal system associated with a variety of physiological and pathological processes such as infection, clearance, inflammation, and apoptosis." (PMID 30404247, 2018). "Analysis of CTSB levels in CVB3-infected murine acinar cell line 266-6 revealed a time- and dose-dependent increase in CTSB protein expression post-infection (p.i.)." (PMID 41277866, 2026). "Downregulating CTSB by transfecting cells with CTSB-siRNA 36 h prior to infection reduced VP1 protein in the exosomes." (PMID 41277866, 2026). "The expression levels in the four primary immune-related tissues (gills, kidneys, liver, and spleen) induced by pathogen infection appeared to be different, which indicated the participation of CTSB in the immunological response." (PMID 40422803, 2025). "In BALB/c mice infected with a laboratory strain A/HKx31(H3N2), lung DCs showed increased CtsB levels and activity 30 days post-infection." (PMID 41369389, 2025). "Removal of cathepsin B would therefore present an additional advantage in avoiding inflammatory cell death and clearance of infection." (PMID 40274809, 2025).
infection (continued). "Lysosomal membrane permeabilization (LMP), triggered by oxidative stress during infection, releases cathepsin B and acid hydrolases into the cytosol, activating pro-apoptotic proteins such as Bid, Bad, and Bax." (PMID 41305332, 2025). "Live cell labelling of THP-1 cells with BMV109 confirmed that cathepsin B activity is lost during infection, with other cysteine cathepsins showing increased or unchanged activity." (PMID 40274809, 2025). "We observed equivalent cathepsin B secretion during infection with WT and icmL::Tn C. burnetii, which increased with MOI." (PMID 40274809, 2025). "Proteomic analysis further confirmed increased abundance of cathepsin B during infection with cvpB::Tn compared to wild type." (PMID 40274809, 2025). "Using this approach, we observed that the peptide 72VMFTEDLK79 from the pro-domain of cathepsin B increased in abundance during infection, in contrast to decreased abundance of peptides within the mature protein." (PMID 40274809, 2025). "Many genes in the autophagy and mitophagy signaling pathways, such as ULK2, BNIP3, WIPI1 and CTSB, presented significantly upregulated expression profiles following infection." (PMID 39650642, 2024). "Our results showed that CATH-2 pretreatment significantly inhibited the mRNA transcription of CTSB at 6 h post-infection." (PMID 39684284, 2024). "Another significant and novel finding from this study is that protein expression of cathepsin B was found to be augmented after infection of CF cells with M. avium." (PMID 39413095, 2024). "During infection, the cytotoxic effect was diminished by cathepsin B inhibition in BMDMs and RAW264.7 cells." (PMID 37457695, 2023). "We found that hvKp and cKp infection increased the enzymatic activity of cathepsin B in murine macrophages." (PMID 37457695, 2023). "During hvKp and cKp infection, Magic Red, which measures the cathepsin B activity, increased in BMDMs." (PMID 37457695, 2023). "Previous studies have suggested that TMPRSS2 and CTSL/CTSB inhibitors effectively prevent the infection of other coronaviruses, including SARS-CoV, MERS-CoV, and human coronavirus (HCoV)-229E58–60." (PMID 37990007, 2023). "Elevated levels of cathepsin B were observed in the lungs of mice and rabbits following infection with Mtb as well as in plasma from acute TB patients, suggesting that there is an association between increased cathepsin B levels and active disease." (PMID 34421929, 2021). "Expression of ACE2, TMPRSS2, and Cathepsin B in organotypic cultures was consistent with the in vivo distribution of SARS-CoV-2 during the first 4 days of infection." (PMID 34608167, 2021). "Mimicking experiments, we calculated the fraction of infection events ‘unaffected’ by the Cathepsin B/L inhibitor, which we denoted fu(DC)." (PMID 33290397, 2020). "The majority of genes (CANX, B2M, CD74 and CTSB) in Antigen processing and presentation pathway were downregulated during infection." (PMID 33177569, 2020). "Cathepsin B silencing enhanced the VSV-pseudotyped MLV vector infection in both 293T and TE671 cells." (PMID 32635194, 2020). "The expression of LEP and CTSB remained unchanged at 6 h post-infection, whereas CTSL showed down-regulation, which is in agreement with earlier reports." (PMID 32275661, 2020). "We have previously reported that cathepsin B suppresses infection by CD4-independent strains of HIV." (PMID 32635194, 2020). "In the same way, with Vero cells, which hardly express TMPRSS2, camostat mesylate had little effect in reducing SARS-CoV-2 infection, whereas E-64d, which blocked Cathepsin B/L reduced nearly 100% of the infections." (PMID 33290397, 2020). "Although the conformational change of E protein by acidification is sufficient for infection, digestion of the E protein by endosomal cathepsin B protease more efficiently facilitates the membrane fusion activity and enhances infection." (PMID 32635194, 2020).
infection (continued). "NHBE cells were pre-incubated with CA-074-Me cathepsin B inhibitor, before infection with PAO1 and concomitant exposure to LL-37, after which conditioned media was generated and filtered." (PMID 30978238, 2019). "While cathepsin B correlates with resistance to infection, previous studies have identified cathepsin L-like gene upregulation in B. glabrata susceptible to infection from the intestinal fluke Echinostoma caproni." (PMID 31521183, 2019). "Following H37Rv infection, we found increased levels of mature CTSB, cleaved caspase-1, and mature IL-1β from infected macrophages, the latter observation confirming that the changes in IL-1β levels measured by ELISA reflect alterations in the mature cytokine." (PMID 29977244, 2018). "Elevated levels of CTSB was observed in the lungs of mice and rabbits following infection with Mycobacterium tuberculosis (Mtb) H37Rv as well as in plasma from acute tuberculosis patients." (PMID 29977244, 2018). "CTSB enzyme activity was found increased by two-fold in the lungs from mice infected with Mtb on day 30 post-infection and was further elevated after 6 months of infection." (PMID 29977244, 2018). "For example, RNAi-mediated knock down of Trypanosoma brucei cathepsin B leads to clearance of parasites from the bloodstream and prevents lethal infection in mice." (PMID 28190401, 2017). "The Sm-cathepsin B and Montanide formulation conferred protection against a challenge infection by significantly reducing all forms of parasitological burdens." (PMID 26945988, 2016). "Despite the lack of cell death induced by strain Lp02rpsLWT∆flaA at 12 hrs post infection, ctsB-/- BMDMs were unable to support intracellular growth of this strain." (PMID 25738962, 2015). "Similar results were obtained in infections in which strain Lp02rpsLWT induced significantly less cell death in BMDMs from ctsB-/- mice 14 hrs after uptake." (PMID 25738962, 2015). "Our results indicate that in this model of infection, cathepsin B plays a significant role not only in the expression of antigen-presenting MHC class II molecules, but also in the regulation of IL-12 production." (PMID 25255101, 2014). "Cathepsin B appears to be required for NLRP3 activation in response to infection with T. cruzi, as pharmacological inhibition of cathepsin B abrogates IL-1β secretion." (PMID 24098823, 2013). "In a closely related protozoan, Trypanosoma brucei, RNAi targeting of cathepsin B leads to clearance of parasites from the bloodstream and prevents lethal infection in mice." (PMID 24244582, 2013). "Cathepsin B null mutant parasites show significantly reduced number of amastigotes inside macrophages 24 hours after infection, and episomal complementation augments this effect." (PMID 24244582, 2013). "The involvement of L. (L.)chagasi cathepsin B with mouse macrophage infection and parasite survival has been already demonstrated." (PMID 23144968, 2012). "Cathepsin B activity was significantly increased at 3 and 12 days post-infection (p = 0.048 and p = 0.043, respectively)." (PMID 22693552, 2012). "There was a significant increase in cathepsin B mRNA at day 12 compared to day 3 (p = 0.026) and day 7 post-infection (p = 0.038)." (PMID 22693552, 2012). "The endosome acidification inhibitors are thought to enhance the CD4-independent HIV-1 vector infection by suppressing cathepsin B activity, because cathepsin B is activated by low pH in acidic endosomes." (PMID 21541353, 2011). "Inhibition of cathepsin B by the cystatin C expression or by the CA-074Me treatment increases the CD4-independent infection by suppressing the viral particle degradation." (PMID 21541353, 2011). "The inhibitory effect of CD4-TLR4 on the CD4-independent infection was abrogated by treatment with the cathepsin B inhibitor, CA-074Me (10 μM)." (PMID 21541353, 2011). "In contrast, CA-074Me treatment attenuated the CD4-independent vector infection in a dose-dependent manner in 293T cells, whose cathepsin B activity was extremely low." (PMID 21541353, 2011).